ACVR1B (activin A receptor type 1B)
Description:
Transmembrane serine/threonine kinase activin type-1 receptor forming an activin receptor complex with activin receptor type-2 (ACVR2A or ACVR2B). Transduces the activin signal from the cell surface to the cytoplasm and is thus regulating a many physiological and pathological processes including neuronal differentiation and neuronal survival, hair follicle development and cycling, FSH production by the pituitary gland, wound healing, extracellular matrix production, immunosuppression and carcinogenesis. Activin is also thought to have a paracrine or autocrine role in follicular development in the ovary. Within the receptor complex, type-2 receptors (ACVR2A and/or ACVR2B) act as a primary activin receptors whereas the type-1 receptors like ACVR1B act as downstream transducers of activin signals. Activin binds to type-2 receptor at the plasma membrane and activates its serine-threonine kinase. The activated receptor type-2 then phosphorylates and activates the type-1 receptor such as ACVR1B. Once activated, the type-1 receptor binds and phosphorylates the SMAD proteins SMAD2 and SMAD3, on serine residues of the C-terminal tail. Soon after their association with the activin receptor and subsequent phosphorylation, SMAD2 and SMAD3 are released into the cytoplasm where they interact with the common partner SMAD4. This SMAD complex translocates into the nucleus where it mediates activin-induced transcription. Inhibitory SMAD7, which is recruited to ACVR1B through FKBP1A, can prevent the association of SMAD2 and SMAD3 with the activin receptor complex, thereby blocking the activin signal. Activin signal transduction is also antagonized by the binding to the receptor of inhibin-B via the IGSF1 inhibin coreceptor. ACVR1B also phosphorylates TDP2.
Synonyms: SKR2; ACVRLK4; ALK4; ActRIB
Tractability: Small molecule: a high-quality ligand is known; it belongs to a druggable protein family. Antibody: its Gene Ontology location is reachable by antibodies, with high confidence; UniProt places it where antibodies can reach, with medium confidence; UniProt predicts a signal peptide or a membrane-spanning region. PROTAC: UniProt records ubiquitination sites on it; ubiquitination databases record sites on it; its protein half-life has been measured; a small molecule that binds it is known.
Target class: Enzyme; TKL protein kinase group; TKL protein kinase STKR family; TKL protein kinase STKR Type 1 subfamily; Protein Kinase; Kinase
Chemical probes: TP-008 (high quality)
Gene: Protein-coding gene on chromosome 12 (51,951,679 to 51,997,082, forward strand). Ensembl gene ENSG00000135503.
Subcellular location: Cell membrane
Subcellular location (Human Protein Atlas): Cytosol; Primary cilium; Vesicles
Pathways (Reactome):
Developmental Biology: Regulation of signaling by NODAL; Signaling by NODAL
Signal Transduction: Signaling by Activin
Gene Ontology:
Molecular function: activin binding; activin receptor activity; activin receptor activity, type I; ATP binding; growth factor binding; I-SMAD binding; inhibin binding; protein binding; protein serine/threonine kinase activity; SMAD binding; ubiquitin protein ligase binding; transmembrane receptor protein serine/threonine kinase activity; protein kinase activity
Biological process: activin receptor signaling pathway; extrinsic apoptotic signaling pathway; G1/S transition of mitotic cell cycle; negative regulation of cell growth; negative regulation of ossification; nodal signaling pathway; peptidyl-threonine phosphorylation; positive regulation of activin receptor signaling pathway; positive regulation of erythrocyte differentiation; positive regulation of trophoblast cell migration; protein autophosphorylation; regulation of DNA-templated transcription; signal transduction; cell surface receptor protein serine/threonine kinase signaling pathway; cellular response to growth factor stimulus; negative regulation of cell differentiation; nervous system development; regulation of cell migration; regulation of gene expression; regulation of multicellular organismal process
Cellular component: activin receptor complex; cell surface; plasma membrane; receptor complex; membrane
Genetic constraint (gnomAD): Loss-of-function variants: 15 observed, 57.29 expected, observed/expected ratio (o/e) 0.26, 90% interval 0.17 to 0.4. The upper end of that interval is the gene's LOEUF score, 0.4, which puts it in group 1 of 6, group 1 being the genes least tolerant of losing a copy. Missense variants: 359 observed, 684.93 expected, observed/expected ratio (o/e) 0.52, 90% interval 0.48 to 0.57. Synonymous variants: 247 observed, 258.64 expected, observed/expected ratio (o/e) 0.96, 90% interval 0.86 to 1.06.
Homologues: Orthologues: chimpanzee ACVR1B (99% identical), macaque ACVR1B (99% identical), pig ACVR1B (99% identical), dog ACVR1B (98% identical), mouse Acvr1b (98% identical), rat Acvr1b (95% identical), guinea pig ACVR1B (95% identical), rabbit ACVR1B (93% identical), tropical clawed frog acvr1b (84% identical), zebrafish acvr1ba (79% identical), zebrafish acvr1bb (78% identical), Drosophila melanogaster babo (55% identical), and 3 more. Paralogues in human: TGFBR1 (68% identical), ACVR1C (63% identical), BMPR1B (49% identical), BMPR1A (49% identical), ACVR1 (48% identical), ACVRL1 (46% identical), ACVR2B (30% identical), TGFBR2 (30% identical), ACVR2A (29% identical), BMPR2 (27% identical), AMHR2 (27% identical).
Diseases named in the same sentence as ACVR1B in open-access papers:
ACVR1B is named in the same sentence as 80 diseases in open-access papers, as found by Europe PMC text mining. Sharing a sentence is not in itself a finding about the gene and the disease. The quoted sentences say what the papers report.
pancreatic cancer (18 papers, 2009 to 2025). "For instance, homozygous deletion of acvr1b is associated with an aggressive cancer phenotype in pancreatic cancer." (PMID 32066878, 2020). "Somatic ACVR1B gene mutations have been found in pancreatic carcinoma and Smad2 and Smad4 are mutated in colorectal and pancreatic carcinomas." (PMID 19538713, 2009). "Low ACVR1B expression was significantly associated with reduced recurrence-free survival in breast cancer patients and with significantly decreased overall survival in pancreatic cancer patients." (PMID 41408046, 2025). "Additionally, ACVR1B is commonly mutated in pancreatic cancer, and in a majority of sporadic colorectal cancers BMPR2 expression is impaired." (PMID 26447543, 2015). "Functional activation and overexpression of the components of the activin/nodal signaling pathway including Nodal, Cripto-1, FoxH1, Smad2, Smad4, Gdf1, activin, and ACVR1B were detected in primary pancreatic cancer stem cells (CSC)." (PMID 34356885, 2021). "In cancer studies, there are several researches showing different roles of ACVR1B based on different cancer types, such as tumor-suppressor role in pancreatic cancer, oncogenic roles in small-bowel adenocarcinoma, prostate cancer, and leukemia." (PMID 32066878, 2020). "Somatic biallelic inactivation of ACVR1B has been reported in pancreatic cancer." (PMID 34356885, 2021). "Using data from TCGA, CPTAC-PAAD, QCMG-PAAD, and METABRIC-BRCA, we stratified patients with pancreatic cancer (PAAD) and breast cancer (BRCA) into top and bottom quartiles of ACVR1B expression and then performed gene set enrichment analysis (GSEA) using EMT and cancer-associated gene signatures." (PMID 41408046, 2025). "In both breast and pancreatic cancer cells, we observed a significant negative correlation between ACVR1B expression and ACVR1B methylation levels, suggesting that ACVR1B methylation is a critical mechanism driving ACVR1B silencing." (PMID 41408046, 2025). "Pathway analysis of its target genes via DAVID showed enrichment (FDR < 5 %) of genes in the Jak-Stat signaling pathway, including several receptors of interleukins (PTPN6, IL22RA1, CREBBP, IL28RA, IL15RA, PIK3R5, STAT3) and pancreatic cancer pathways (VEGFC, ACVR1B, PIK3R5, EGF, STAT3)." (PMID 26572553, 2015). "Similarly, in pancreatic cancer, tumor samples exhibited significantly higher ACVR1B methylation levels compared to adjacent normal tissues, and 5-AZA treatment also significantly upregulated ACVR1B expression in pancreatic cancer cells." (PMID 41408046, 2025).
breast carcinoma (13 papers, 2011 to 2025). "Furthermore, lower ACVR1B expression was associated with worse recurrence-free survival in basal-like breast cancer patients." (PMID 41408046, 2025). "Among these, only ETS1 showed a strong negative correlation with ACVR1B and a positive correlation with MGAT5 in TCGA pancreatic and breast cancer cohorts, implicating ETS1 in ALK4 loss-mediated MGAT5 upregulation." (PMID 41408046, 2025). "Moreover, reduced ACVR1B expression correlated with poorer recurrence-free survival in breast cancer patients with high Ki67 proliferation indices." (PMID 41408046, 2025). "Importantly, ACVR1B expression was significantly lower in basal-like breast cancer compared to Luminal A (LumA), LumB, and HER2-enriched subtypes." (PMID 41408046, 2025). "In four main subtypes of breast cancer, elevated expression of BMPR1B and ACVR2B were seen in Luminal A subtype, while BMP4, GDF15 and ACVR1B were higher in Luminal B, TGFBR1 and BMP8A were higher in HER2 positive, BMP2, BMP6 and GDF5 were higher in TNBC." (PMID 37333824, 2023). "Furthermore, higher levels of BMP2, BMP6 and GDF5 were revealed in triple negative breast cancer (TNBC) whilst BMP4, GDF15, ACVR1B, ACVR2B and BMPR1B were relatively higher in Luminal type BC." (PMID 37333824, 2023).
myeloma (5 papers, 2015 to 2022). "The underlying mechanism of ActivinA/SMAD1/5 signaling is not fully understood but suggests ACVR1 dependency and independency of ACVR1B/C/TGFBR1 as demonstrated by inhibitor experiments in FOP iECs being in line with knockdown studies in FOP and myeloma cells." (PMID 33410098, 2021).
colon cancer (4 papers, 2014 to 2025). "Small molecule inhibitors for both TGFBR1/2 and ACVR1B are available and conceivably could be used as adjuvant therapies in advanced colon cancer, but biomarkers to determine treatment suitability and specifically to avoid augmentation of oncogenic signaling are lacking." (PMID 26497569, 2015).
colorectal cancer (4 papers, 2014 to 2021). A primary or metastatic malignant neoplasm that affects the colon or rectum. "Analysis of expressed mutated surface genes revealed recurrent mutations in genes belonging to pathways known to be involved in colorectal cancer, including the WNT (LRP5 and FZD10), TGFβ (TGFBR3 and ACVR1B) and RTK-Ras (EGFR and ERBB3) signaling pathways." (PMID 25193853, 2014).
lung carcinoma (4 papers, 2011 to 2023). "Of note, however, single nucleotide polymorphisms (SNP) in the ACVR1B gene have been associated with increased risk of lung cancer from tobacco smoke exposure." (PMID 37020544, 2023). "The ACVR1B gene was correlated with the risk of lung cancer in adults exposed to environmental tobacco smoke; similarly, ACVR1B was associated with poor prognosis in the present study." (PMID 34036102, 2021). "Similarly, a SNP variant was found in never-smoking lung cancer patients, indicating the potential driving role of ACVR1B in NSCLC." (PMID 34150632, 2021). "In human lung cancer CL1-5 cells, ACVR1B (1.5-fold) and ID1 (inhibitor of DNA binding 1, dominant negative helix-loop-helix protein, 1.3-fold) were observed to be up-regulated, while LTBP3 (latent TGF-β binding protein 3, 1/1.6-fold) was down-regulated." (PMID 21998723, 2011).
prostate carcinoma (4 papers, 2016 to 2022). A carcinoma that arises from epithelial cells of the prostate gland. "In prostate cancer cells acvr1b promoted lymph node metastasis." (PMID 32066878, 2020).
Sepsis (4 papers, 2022 to 2025). Sepsis is defined as life-threatening organ dysfunction caused by a dysregulated host response to infection. "Moreover, ACVR1B expression is upregulated in septic melioidosis, a widespread cause of fatal sepsis in the tropics." (PMID 37020544, 2023). "In macrophages, we observed that the induction of pSmad3C was abrogated in Acvr1b-Lyz2cre mice, indicating that activin A is indeed indispensable for Smad3 activation in sepsis models induced by LPS and CLP surgery." (PMID 40067393, 2025). "The current body of literature on the overlap of ACVR1B on one hand and sepsis, inflammation, or neutrophil on the other hand was assessed." (PMID 37020544, 2023). "Here, we report the upregulation of the ACVR1B gene during sepsis in human melioidosis and discuss additional possible avenues to investigate its putative role in the pathogenesis of sepsis." (PMID 37020544, 2023). "As a first step to bridging the gap between the postulated upregulation of ACVR1B in sepsis and the rational for this observation, another systematic literature search was conducted in PubMed." (PMID 37020544, 2023). "We provided evidence that the ACVR1B gene is upregulated during sepsis, a finding that is substantiated by its known physiological role (e.g., in cell proliferation and apoptosis)." (PMID 37020544, 2023). "Strong evidence (p < 0.05) for an increased ACVR1B expression in sepsis was found in 6 out of 11 datasets." (PMID 37020544, 2023). "Using a reductionist approach leveraging publicly available transcriptomic data, we describe a knowledge gap for the role of ACVR1B (activin A receptor type 1B) in sepsis." (PMID 37020544, 2023). "Based on our re-investigation of publicly available transcriptomic data and newly generated ex vivo data, we provide perspective on the role of ACVR1B during sepsis." (PMID 37020544, 2023). "We confirmed our observations by measuring ACVR1B transcript abundance in buffy coat samples obtained from healthy individuals (n=3) exposed to septic plasma (n = 26 melioidosis sepsis cases)ex vivo." (PMID 37020544, 2023). "Although induction of ACVR1B transcription was observed in several cohort studies assessing adult and pediatric sepsis, additional experimental data are necessary to confirm the role of ACVR1B in sepsis." (PMID 37020544, 2023). "In a Boolean search, no overlap was found between the ACVR1B literature and the search term “sepsis”." (PMID 37020544, 2023). "Notably, to our knowledge, ACVR1B which is a cytokine receptor and TGF-β family member receptor, was firstly identified to be related to both trauma and sepsis in the present study." (PMID 35615364, 2022). "Interestingly, the expression of Inhba, Smad3, Acvr1b, Acvr2a, Stat5a, and Stat5b was all higher in the macrophages of patients compared with healthy volunteers, suggesting that the activin A/Smad3/STAT5 axis is also involved in human sepsis." (PMID 40067393, 2025).
breast tumor (3 papers, 2012 to 2025). "ACVR1C, TGFBR2, TGFBR3, ACVR2A, ACVR1, BMPR1A and BMPR2 were lower in breast tumours while ACVR1B and BMPR1B exhibited relatively higher expression levels in paired tumours compared with normal breast tissues, in the TCGA_BRCA cohort." (PMID 37333824, 2023).
emphysema (3 papers, 2023). "ACVR1B expression levels are nominally significantly associated with emphysema distribution." (PMID 37516822, 2023). "In a gene analysis study, ACVR1B has been identified as a validated relevant gene of emphysema, a subtype of progressive airflow obstruction accompanied by chronic inflammation." (PMID 37085769, 2023).
glioma (3 papers, 2019 to 2025). A benign or malignant brain and spinal cord tumor that arises from glial cells (astrocytes, oligodendrocytes, ependymal cells). "However, little is known about the role of ACVR1B and PODXL2 on gliomas." (PMID 31118022, 2019).
lung adenocarcinoma (3 papers, 2018 to 2022). A carcinoma that arises from the lung and is characterized by the presence of malignant glandular epithelial cells. "The result revealed that ACVR1B was associated with poor prognosis in lung adenocarcinoma (HR = 1.713, P < 0.1), and it indicated that ACVR1B might have potential value in further research." (PMID 34122500, 2021). "Our primary screen generated a functionally annotated list of 28 genes that led to robust metastatic dissemination and merit further interrogation, including some that have been previously identified to be mutated in lung adenocarcinoma (GNAS, MAPK6, ACVR1B, FBXW7, NTRK3)." (PMID 30013058, 2018). "We identified three genes (GATAD2B, ACVR1B, and ZC3H11A) whose overexpression significantly correlates with mutant KRAS lung adenocarcinoma vs wild-type KRAS status in patients." (PMID 30013058, 2018).
hepatocellular carcinoma (2 papers, 2016 to 2020). A malignant tumor that arises from hepatocytes. "Overexpression of ACVR1B, a key receptor of bone morphogenetic proteins (BMPs) and an important regulator of the BMP/Wnt signaling pathway and, therefore, for cancer stem cells, was associated with clinically aggressive and poor survival in hepatocellular carcinoma." (PMID 33066614, 2020).
ischemic stroke (2 papers, 2022 to 2023). A stroke disorder caused by obstruction of blood flow to the brain, due to thrombotic (local blood clot formation) or embolic (due to a blood clot or other material traveling from another site) event. "Increased levels of myelin-associated proteins, including Mag and Mbp proteins, were demonstrated through Activin A oligodendroglial ACVR1B-mediated white matter remyelination after ischemic stroke in mice." (PMID 37965042, 2023). "Additionally, the neuroprotective role of its gene target ACVR1B in promoting remyelination has been reported previously in a mouse model of ischemic stroke." (PMID 36613546, 2022).
latent infection (2 papers, 2016). "This suggests that latent infection increases the expression of ACVR1B, which is then returned to basal levels by miR-UL148D." (PMID 27491954, 2016). "In order to confirm that this effect of miR-UL148D on ACVR1B also occurred specifically in the context of latent infection, we next analysed expression of ACVR1B in monocytes latently infected with WT virus or with a virus lacking miR-UL148D." (PMID 27491954, 2016). "Consistent with this, we observed upregulation of ACVR1B expression during latent infection with a miR-UL148D deletion virus (ΔmiR-UL148D)." (PMID 27491954, 2016). "However, miR-UL148D clearly targets ACVR1B, both in isolation and during experimental latent infection, suggesting that perturbation of other myeloid-specific functions of ACVR1B is important during latency." (PMID 27491954, 2016). "Furthermore, we demonstrate that miR-UL148D, one of the most highly expressed viral miRNAs during latent infection, directly targets the cellular receptor ACVR1B of the activin signalling axis." (PMID 27491954, 2016). "The ability of WT virus or ΔmiR-UL148D to affect ACVR1B during latent infection was then analysed." (PMID 27491954, 2016). "On the basis that miR-UL148D was expressed at high levels during latent infection and clearly targeted ACVR1B, we next asked whether miR-UL148D played any role in cellular functions important for latent carriage and/or reactivation in primary monocytes models of latency." (PMID 27491954, 2016). "Whilst latent infection of monocytes, in itself, did not alter the low level of ACVR1B, levels of this receptor were upregulated during latent infection in monocytes in which miR-UL148D had been deleted." (PMID 27491954, 2016).
pancreatic ductal adenocarcinoma (2 papers, 2020 to 2025). An infiltrating adenocarcinoma that arises from the epithelial cells of the pancreas. "For example, in pancreatic ductal adenocarcinoma (Panc-AdenoCA; N = 232), the addition of functional adjustment to the algorithm resulted in a gain of three additional drivers (ACVR1B, RBM10 and ZFP36L2) and the loss of one likely false-positive genes (FAU)." (PMID 32024818, 2020). "Interestingly, the Activin Signalling Pathway is known to function as both–a tumor-suppressor and a tumor-initiator in cancer, although this phenomenon was initially described for ACVR1B in pancreatic ductal adenocarcinoma (PDAC)." (PMID 39958888, 2025).